HLA-DRB5 (major histocompatibility complex, class II, DR beta 5)
Description:
Binds peptides derived from antigens that access the endocytic route of antigen presenting cells (APC) and presents them on the cell surface for recognition by the CD4 T-cells. The peptide binding cleft accommodates peptides of 10-30 residues. The peptides presented by MHC class II molecules are generated mostly by degradation of proteins that access the endocytic route, where they are processed by lysosomal proteases and other hydrolases. Exogenous antigens that have been endocytosed by the APC are thus readily available for presentation via MHC II molecules, and for this reason this antigen presentation pathway is usually referred to as exogenous. As membrane proteins on their way to degradation in lysosomes as part of their normal turn-over are also contained in the endosomal/lysosomal compartments, exogenous antigens must compete with those derived from endogenous components. Autophagy is also a source of endogenous peptides, autophagosomes constitutively fuse with MHC class II loading compartments. In addition to APCs, other cells of the gastrointestinal tract, such as epithelial cells, express MHC class II molecules and CD74 and act as APCs, which is an unusual trait of the GI tract. To produce a MHC class II molecule that presents an antigen, three MHC class II molecules (heterodimers of an alpha and a beta chain) associate with a CD74 trimer in the ER to form a heterononamer. Soon after the entry of this complex into the endosomal/lysosomal system where antigen processing occurs, CD74 undergoes a sequential degradation by various proteases, including CTSS and CTSL, leaving a small fragment termed CLIP (class-II-associated invariant chain peptide). The removal of CLIP is facilitated by HLA-DM via direct binding to the alpha-beta-CLIP complex so that CLIP is released. HLA-DM stabilizes MHC class II molecules until primary high affinity antigenic peptides are bound. The MHC II molecule bound to a peptide is then transported to the cell membrane surface. In B-cells, the interaction between HLA-DM and MHC class II molecules is regulated by HLA-DO. Primary dendritic cells (DCs) also to express HLA-DO. Lysosomal microenvironment has been implicated in the regulation of antigen loading into MHC II molecules, increased acidification produces increased proteolysis and efficient peptide loading.
Synonyms: DRB5; HLA-DRB5*
Tractability: Small molecule: it has a binding pocket of medium quality. Antibody: a drug acting on it is in phase 2 or 3 trials; UniProt places it where antibodies can reach, with high confidence; its Gene Ontology location is reachable by antibodies, with high confidence; UniProt predicts a signal peptide or a membrane-spanning region. PROTAC: UniProt records ubiquitination sites on it.
Gene: Protein-coding gene on chromosome 6 (32,517,345 to 32,530,369, reverse strand). Ensembl gene ENSG00000198502.
Subcellular location: Cell membrane; Endoplasmic reticulum membrane; Golgi apparatus, trans- Golgi network membrane; Endosome membrane; Lysosome membrane; Late endosome membrane
Pathways (Reactome):
Immune System: Co-inhibition by PD-1; Downstream TCR signaling; Generation of second messenger molecules; Interferon gamma signaling; MHC class II antigen presentation; Phosphorylation of CD3 and TCR zeta chains; Translocation of ZAP-70 to Immunological synapse
Gene Ontology:
Molecular function: protein binding; MHC class II protein complex binding; peptide antigen binding
Biological process: antigen processing and presentation of exogenous peptide antigen via MHC class II; peptide antigen assembly with MHC class II protein complex; positive regulation of immune response; positive regulation of T cell activation; antigen processing and presentation; immune response
Cellular component: extracellular exosome; late endosome membrane; lysosomal membrane; clathrin-coated endocytic vesicle membrane; endocytic vesicle membrane; ER to Golgi transport vesicle membrane; Golgi membrane; lumenal side of endoplasmic reticulum membrane; MHC class II protein complex; plasma membrane; trans-Golgi network membrane; transport vesicle membrane; endoplasmic reticulum membrane; endosome membrane; Golgi apparatus; membrane
Genetic constraint (gnomAD): Loss-of-function variants: 6 observed, 5.22 expected, observed/expected ratio (o/e) 1.15, 90% interval 0.61 to 1.86. That is too few expected variants to judge how well the gene tolerates losing a copy. Missense variants: 55 observed, 73.85 expected, observed/expected ratio (o/e) 0.74, 90% interval 0.6 to 0.93. Synonymous variants: 37 observed, 28.67 expected, observed/expected ratio (o/e) 1.29, 90% interval 0.99 to 1.69.
Homologues: Orthologues: chimpanzee PATR-DRB5 (91% identical), macaque MAMU-DRB1 (87% identical), mouse H2-Eb2 (63% identical). Paralogues in human: HLA-DRB1 (89% identical), HLA-DQB2 (65% identical), HLA-DQB1 (64% identical), HLA-DPB1 (58% identical), HLA-DOB (55% identical), HLA-DQA1 (21% identical), HLA-DRA (21% identical), HLA-DOA (21% identical), HLA-DQA2 (21% identical), HLA-DMB (20% identical), HLA-DPA1 (20% identical), HLA-DMA (17% identical), and 1 more.
Diseases named in the same sentence as HLA-DRB5 in open-access papers:
HLA-DRB5 is named in the same sentence as 120 diseases in open-access papers, as found by Europe PMC text mining. Sharing a sentence is not in itself a finding about the gene and the disease. The quoted sentences say what the papers report.
COVID-19 (13 papers, 2021 to 2025). A disease caused by infection with severe acute respiratory syndrome coronavirus 2. "This analysis confirmed previous reports of downregulation of HLA genes such as HLA-DRA and HLA-DRB5 in COVID-19 patients, with severe patients showing the most downregulation." (PMID 35007307, 2022). "Our DEG analysis showed increased levels of HLA-DRA, HLA-DRB1 and HLA-DRB5 in CD16+ monocytes from mild COVID-19 cases compared to healthy donors." (PMID 34108966, 2021). "Expression levels of major histocompatibility complex class II molecules, including HLA-DRA, HLA-DRB5, HLA-DPA1, and HLA-DQB1, which are expected to be increased following MAC activation in the COVID-19 group, were found to decrease." (PMID 38441496, 2024). "Differential expression analysis in the scRNA-seq revealed that MHC class II genes, such as HLA-DRB5, HLA-DPB1, HLA-DPA1, HLA-DRB1, and HLA-DRA, were downregulated in convalescent COVID-19 individuals." (PMID 35464396, 2022). "There was also significant upregulation of MHC-II expression (HLA-DRB5, HLA-DQB2, HLA-DPB1, etc.) in mild COVID-19 patients." (PMID 33473155, 2021). "Furthermore, we found significant downregulation of most of HLA class II genes (HLA-DRB5, HLA-DQB1 and HLA-DQA2, etc.)in B cells from COVID-19 patients, especially in the severe and acute necrotizing encephalopathy groups, indicating dysregulated crosstalk between adaptive immune cells." (PMID 37848421, 2023). "Interestingly, MSCs from patients with mild COVID-19 transcribed high levels of CD86, HLD-DRA, HLA-DRB1, and HLA-DRB5, suggesting that these cells may play a role in the priming of T lymphocytes and act directly and indirectly in the orchestration of the immune response facing the disease." (PMID 35095855, 2021).
rheumatoid arthritis (11 papers, 2012 to 2025). A chronic, systemic autoimmune disorder characterized by inflammation in the synovial membranes and articular surfaces. "The SNP rs2395185 and the two cis-mediators, HLA-DRB5 and HLA-DRB1, were reported to be susceptible to ulcerative colitis, and the two HLA genes were also identified in the rheumatoid arthritis GWAS." (PMID 30925861, 2019). "It has been reported that a lack of HLA-DRB5 may be associated with various diseases, including rheumatoid arthritis patients with negative antibodies against citrullinated peptides and patients with multiple sclerosis." (PMID 41409291, 2025). "Interestingly, the rs1964995 SNP located between HLA-DRB9 and HLA-DRB5, a risk SNP only in AAs in our study, was protective in a Swedish cohort with non-Lofgren sarcoidosis GWAS, but increased the risk of rheumatoid arthritis in ADs, but not in EDs." (PMID 38390497, 2023). "A resent genome-wide association study has identified several shared loci (including HLA-DRB5, LRRK2, and MAPT) between PD and 7 autoimmune diseases (including psoriasis, rheumatoid arthritis, and so on), suggesting that there were some common genetic risks between PD and autoimmune diseases." (PMID 31929812, 2019). "The genetic association of HLA-DRB1 with rheumatoid arthritis (RA) and systemic lupus erythematosus (SLE) is well documented, but association with other HLA-DR beta genes (HLA-DRB3, HLA-DRB4 and HLA-DRB5) has not been thoroughly studied, despite their similar functions and chromosomal positions." (PMID 26919467, 2016).
multiple sclerosis (10 papers, 2013 to 2025). A progressive autoimmune disorder affecting the central nervous system resulting in demyelination. "The HLA-DRB5 gene is involved in genetic susceptibility to multiple sclerosis (MS) as HLA-DRB5 null subjects appear to be at increased risk for developing secondary progressive MS." (PMID 26052346, 2015). "The associations of HLA-DRB5 with autoimmune disorders such as multiple sclerosis, systemic sclerosis, and rheumatic heart disease have been reported." (PMID 23326468, 2013). "Several HLA genes that play a major role in the immune response (including HLA-B/C, HLA-DRB1, and HLA-DRB5) were associated with 2 or more regional volumes and simultaneously with demyelinating diseases, including multiple sclerosis, a prominent immune-mediated disorder." (PMID 39269986, 2024). "For Multiple Sclerosis, an autoimmune condition, differential methylation in multiple HLA-DR loci in the blood reflects this fact, being corroborated by the increased expression of HLA-DRB1 and HLA-DRB5 in the brain of Multiple Sclerosis patients." (PMID 39060467, 2024). "Several studies have pointed out that HLA-DRB5 plays an important role in Alzheimer disease and multiple sclerosis, while the role of HLA-DRB5 in tumors has not been reported." (PMID 36776357, 2022).
type 1 diabetes (8 papers, 2014 to 2025). "While HLA-DRB5 has been linked to type 1 diabetes (T1D), its involvement in T2D remains unclear, with limited evidence supporting an association between the two, presumably in the direction of the gene causing the disease rather than vice versa." (PMID 40663565, 2025). "Of the remaining five genes, three [MICA, NCR3, and TAP2] have been previously associated with type 1 diabetes, while APOM and HLA-DRB5 have been associated with RA." (PMID 32245788, 2020). "This was also reflected in the KEGG pathway analysis of trans-mQTLs where type 1 diabetes was found to be an enriched pathway of relevance in human pancreatic islets, including the following genes: PTPRN2, HLA-DRB1, HLA-B, HLA-C, HSPD1 and HLA-DRB5 (Padj = 6.0×10−4)." (PMID 25375650, 2014).
Alzheimer disease (7 papers, 2015 to 2023). A progressive, neurodegenerative disease characterized by loss of function and death of nerve cells in several areas of the brain leading to loss of cognitive function such as memory and language. "HLA-DRB5 (Major Histocompatibility Complex, Class II, DR Beta 5), whose expression products play a central role in the immune system by presenting peptides derived from extracellular proteins, was found to have a possible pathogenic effect Alzheimer’s disease (AD) risk." (PMID 34868249, 2021). "Differences in gene-wide DNA methylation of the Alzheimer’s disease (AD)-associated genes BIN1, HLA-DRB5, SORL1, SLC24A4, and ABCA7 are reported to be associated with AD in post-mortem brain samples." (PMID 36573011, 2023). "We found HLA-DRB5 is dark by depth in the ADSP and gnomAD data and has been implicated in several diseases, including Alzheimer’s disease." (PMID 31104630, 2019). "Genetic studies including genome-wide studies have also associated inflammation-related genes to the etiology of Alzheimer’s disease (i.e. ABCA7, CLU, CR1, HLA-DRB1, HLA-DRB5, PICALM, and TREM2), further supporting the concept of neuroinflammation as a pathogenic factor in Alzheimer’s disease." (PMID 34335238, 2021). "While PTK2B, IL8 and HLA-DRB5 are clearly involved in Alzheimer pathology, there are controversial studies about the involvement of PICALM in Alzheimers disease." (PMID 25765079, 2015).
autoimmune disease (7 papers, 2013 to 2025). A disorder resulting from loss of function or tissue destruction of an organ or multiple organs, arising from humoral or cellular immune responses of the individual to their own tissue constituents. "It is also noteworthy that one of the molecular networks that resulted from the functional analysis enclose HLA-DRB1 and HLA-DRB5 that have been confirmed implicated in MS and other autoimmune diseases as well as in AD and other NDs." (PMID 39325116, 2024). "The activation of CD8+ T cells via HLA-DRB5 is a recognized mechanism in autoimmune disorders." (PMID 40427057, 2025). "Furthermore, our TWAS research identified novel susceptibility genes for DKD, including HLA-DRB5, a well-characterized MHC-II antigen-presenting molecule implicated in the pathogenesis of various autoimmune diseases." (PMID 40427057, 2025). "GSTT1 has been linked to breast cancer, NAFLD to non-alcoholic fatty liver disease, and HLA-DRB5 and HLA-DQA1 to autoimmune diseases." (PMID 23594316, 2013).
Parkinson disease (7 papers, 2012 to 2024). A progressive degenerative disorder of the central nervous system characterized by loss of dopamine producing neurons in the substantia nigra and the presence of Lewy bodies in the substantia nigra and locus coeruleus. "Other DMPs found were within the genes HLA-DRB5 or YWHAG, which have also been identified as risk factors in the development of FTD and Parkinson’s disease, respectively." (PMID 38791483, 2024). "The genetic variability of HLA-DRB5 is also evidence in favor of a possible genetic relationship between MS and parkinsonism as it has a role in the inflammatory processes in both diseases." (PMID 35601204, 2022). "Recently, HLA-DRB5/DRB1 has been shown to be associated with multiple sclerosis and Parkinson’s disease (PD)." (PMID 29056900, 2017).
ulcerative colitis (6 papers, 2013 to 2021). An inflammatory bowel disease involving the mucosal surface of the large intestine and rectum. "HLA-DRB5 encodes an HLA class II protein which is specific to antigen presentation for immune cells and is related to ulcerative colitis." (PMID 34704776, 2021). "The SNP at the HLA-DRB1/HLA-DRB5 locus associated with ΔHRex in females was also significantly associated with inflammatory bowel disease and ulcerative colitis." (PMID 29769521, 2018). "For HLA-DRB5 rs17425622, it is a risk locus for UC (ulcerative colitis)." (PMID 34868249, 2021).
psoriasis (5 papers, 2017 to 2025). An autoimmune condition characterized by red, well-delineated plaques with silvery scales that are usually on the extensor surfaces and scalp. "Specifically, SNP rs2516049 on chromosome 6, near HLA-DRB5, was associated with both psoriasis and AD, with a consistent direction of effect." (PMID 41465136, 2025). "Nevertheless, the identification of rs2516049 near HLA-DRB5 provides strong evidence that psoriasis and AD share immune-related genetic susceptibility." (PMID 41465136, 2025). "Among inflammatory dermatoses, psoriasis exhibits the strongest overlap with dementia genetics, with shared susceptibility loci including APOE, IL12B, and HLA-DRB5, and transcriptional regulators such as ZNF384 that converge on IL-17/TNF signaling." (PMID 41465136, 2025). "In contrast to the other healthy subjects, CON09 (a patient with psoriasis) expressed the long transcript variant of HLA-DRB1 and a high level of HLA-DRB5 protein, similar to patients in the NM group." (PMID 28052121, 2017). "Beyond candidates, pleiotropy-informed GWAS identify shared HLA architecture (rs2516049 near HLA-DRB5) with concordant effects on psoriasis and AD and correlations with tau pathology and cognitive decline, implicating antigen presentation in both skin and brain." (PMID 41465136, 2025). "Of interest, we identified 3 overlapping DEGs (HEATR6, HLA-DRB5, and MRPL54) between psoriasis neutrophils with and without stimulation of keratinocytes in relative to healthy neutrophils." (PMID 35401573, 2022).
inflammatory bowel disease (4 papers, 2018 to 2025). A spectrum of small and large bowel inflammatory diseases of unknown etiology. "The HLA-DRB5 locus, which has been previously suggested as a potential genetic overlap between inflammatory bowel disease and PD15, exhibited high PAR for the rs112485576 variant." (PMID 39371162, 2025).
influenza (4 papers, 2020 to 2023). An acute viral infection of the respiratory tract, occurring in isolated cases, in epidemics, or in pandemics; it is caused by serologically different strains of viruses (influenzaviruses) designated A, B, and C, has a 3-day incubation period, and usually lasts for 3 to 10 days. "Polymorphism near HLA-DQA2 has previously been associated with mild influenza (H1N1) susceptibility, whereas HLA-DRB5 associates with RA, white blood cell counts, and a dozen other traits." (PMID 36793127, 2023). "Specifically, influenza samples maintained higher levels of type I IFN response–associated antiviral ISGs (e.g., IFITM1, IFITM2, IFITM3, OAS2, OAS3, OASL) and antigen presentation genes (e.g., HLA-DRB5, HLA-C, B2M, HLA-B, HLA-E)." (PMID 34618691, 2021).
lung carcinoma (4 papers, 2017 to 2025). "Previous studies have shown downregulation of SECISBP2L and HLA-DRB5 in lung cancer, with HLA-DRB5 expression inversely correlated with LUAD risk." (PMID 39092217, 2024). "The biological functions of newly discovered HLA-DRB5 and CCDC50 risk genes in lung cancer were further explored." (PMID 36147484, 2022). "Recent studies have shown that high-risk lung cancer groups have significantly lower HLA-DRB5 expression than normal samples and low-risk groups, with HLA-DRB5 being significantly lower in malignant epithelial cells than in normal ones." (PMID 40786043, 2025).
lymphoma (4 papers, 2013 to 2021). A malignant (clonal) proliferation of B- lymphocytes or T- lymphocytes which involves the lymph nodes, bone marrow and/or extranodal sites. "Although the selective basis of these lesions remains unclear, genome-wide association studies in chronic lymphocytic leukaemia and lymphoma have identified germline variants in HLA-DRB5 influencing disease risk." (PMID 34753926, 2021).
melanoma (4 papers, 2001 to 2025). A malignant, usually aggressive tumor composed of atypical, neoplastic melanocytes. "One TCRVbeta6.7+ clone recognized the HLA-DRB5*0101+ FM3 melanoma cell line transfected with a full length HER-2/neu cDNA." (PMID 11720440, 2001). "Other research found that class II molecules (HLA-DPA1, HLA-DPB1, HLA-DQA1, HLA-DRA, HLA-DRB1, HLA-DRB5) are important biomarkers in the occurrence and progression of melanoma tumors, and their expression levels are closely related to prognosis and immune infiltration." (PMID 39969704, 2025). "The results indicated that HLA-DRB5 had significantly higher mutation frequency in responders and the B2M mutations only occurred in non-responders in melanoma." (PMID 36139377, 2022).